CD86 (CD86 molecule)
Diseases named in the same sentence as CD86 in open-access papers (continued):
Sharing a sentence is not in itself a finding about the gene and the disease.
tumor (continued). "Tumor-associated macrophages were also profiled, and an increased M1 (phagocytic, CD206-CD86+)/M2 (proinflammatory, CD206+CD86−) ratio was observed." (PMID 36207308, 2022). "In vivo data showed that oxaliplatin suppressed tumor growth and increased the populations of CD86+CD80+ and CD8+CD45+ cells in the tumor tissues." (PMID 36131787, 2022). "As expected, the proportion of both peripheral and tumor infiltrated activated dendritic cells (CD86+DC) were increased in 4T1 allograft tumors treated with HB3089." (PMID 36513640, 2022). "We found that inhibiting CSF1R or VEGFR significantly reduced the number of CD11b+F4/80+ TAMs and particularly the number and percentage of M2 TAMs (F4/80+CD206+CD86−) generated from co-culture with TAb2 tumor cells." (PMID 35366939, 2022). "Specially, we stained CD68 with green fluorescence and stained CD86 or CD163 with red fluorescence in the tumour tissues by IF co‐localization assay." (PMID 34964155, 2022). "One week after different treatments, the expressions of CD206, CD86 and F4/80 proteins in the tumor tissue were detected by immunofluorescence staining." (PMID 36380062, 2022). "Studies have found that nab-paclitaxel internalization by tumor-associated macrophages can promote the activation of M1 macrophages and increase the MHC II+CD80+CD86+M1 macrophage." (PMID 35719979, 2022). "DC maturation was also studied by detecting the population of matured DCs (CD80+CD86+) in tumor-draining lymph nodes (TDLNs) by flow cytometry analysis." (PMID 35710545, 2022). "The research found that low CD86 expression was significantly correlated with clinicopathological characteristics including tumour differentiation or TNM stage, and high CD86 expression was a favourable predictor for RFS and OS." (PMID 34964155, 2022). "CTLA-4 binds to its ligands B7-1 (CD80) and B7-2 (CD86) to generate inhibitory signals that suppress T cell activation and cytokine production and protect tumor cells from T cell attack." (PMID 36532071, 2022). "On the contrary, cytotoxic T-lymphocyte-associated protein 4 (CTLA4) is a negative regulatory inducible receptor for CD80/CD86 and has inhibitory effects on T cell responses, leading to T cell attenuation and tumor cell immune evasion." (PMID 35656508, 2022). "Nevertheless, upregulation of CD80 and CD86 on tumor cells was observed after treatment with OV-OX40L/IL12 ex vivo or in vivo in our study, suggesting that including some costimulatory ligands is sufficient to jump-start a network of costimulatory signals." (PMID 35715953, 2022). "Specifically, by expressing MHC II, CD74, CD80/CD86 and CD11c, they function as tumor antigen-presenting cells, and activate T cells, leading to tumor cell death and clearance." (PMID 36411434, 2022). "Of note, significantly lower expression of Arg1 and higher expression of CD86 were found in healthy cortex compared with tumor tissue." (PMID 35884700, 2022). "In the combination group, the active form of interferon‐γ (IFN‐γ)‐secreting CD8+ T cells and CD11b+CD86+ M1 macrophages in tumour infiltrating lymphocytes (TILs) were increased." (PMID 35174623, 2022). "Six days after the ADC treatment, there was an elevated expression of CD86 and reduced expression of CD206 in the tumor-associated macrophages." (PMID 36442099, 2022). "We found that there are higher M1 macrophage markers (CD86 and iNOS) in tumor tissues than in normal tissues, accompanied with higher CKAP2L levels in tumor tissues." (PMID 36699449, 2022). "The overexpression of PD-L1 and CD80/CD86 on tumor cells, which can respectively bind to PD-1 and cytotoxic T lymphocyte antigen 4 (CTLA4), results in the inhibition of T cell activation." (PMID 36013050, 2022). "Immune and stromal cell populations included 2 populations: Macrophages 1 (c1: C1qa, C1qb, C3aR1, Cd68, Csf1r, Tlr2, and Cd86) and 2 (c6 + c9: Ccr7, Csf2rb, Il1b, and Cd74) expanded in PNs as a percentage of total tumor cells." (PMID 36134665, 2022).
tumor (continued). "The levels of pro-inflammatory M1 marker CD86 and tumor-killing cytokine TNF-α were significantly up-regulated by PA-MSHA as well." (PMID 36344505, 2022). "A B-cell subset expressing activation markers (CD25+CD69+B7-H1+CD81+CD86+) and termed tumour-evoked Bregs (tBreg) induced the generation of Foxp3+Tregs, which inhibited anti-tumour responses." (PMID 35350071, 2022). "A half of each tumor tissue sample was digested for flow cytometry to examine the portion of F4/80/CD86- or CD206-positive cells." (PMID 36118415, 2022). "oreover, shikonin can improve the expressions of MHC II and CD86, and enhance tumor-immunogenicity of tumor vaccines via ICD." (PMID 36159787, 2022). "Tumor tissues were stained for CD86 (to detect M1-type macrophages) and CD206 (to detect M2-type macrophages), and subjected to immunohistochemical analyses (IHC)." (PMID 36246355, 2022). "Three 20x high-density fields were taken of each tumor section, and Arg1 (as a marker of M2 TAMs), CD86 (as a marker of M1 TAMs), and CD8 (CD8+ Tc) positivity was evaluated using AI trainable WEKA segmentation." (PMID 35634303, 2022). "The increased expression levels of CD40 and CD86 can promote T-cell activation and play an anti-tumor role." (PMID 34034714, 2021). "Further, A20 expressing 4-1BBL in combination with CD80 and CD86 have been observed to be highly immunogenic, thereby inducing durable anti-tumor responses." (PMID 33666760, 2021). "Immunofluorescence confirmed this diversity, as mixed CD206 and CD86 expression was observed for both tumor-infiltrating macrophages and dermal macrophages." (PMID 33959597, 2021). "M1 macrophages, highly expressed major histocompatibility complex class II, CD68 labeling and CD80/CD86 costimulatory molecules, located within tumors are thought to induce tumor suppression by activating anti-tumor immunity." (PMID 35284334, 2021). "CD86 expression demonstrated to be an unfavorable prognostic factor in survival and tumor progression for LGG patients, thereby serving as potential target of immunotherapy." (PMID 33954112, 2021). "In this study, we evaluated the infiltration of macrophages marked with CD86 and CD163 in tumor tissues by the immunohistochemistry technique and focused on CD86/CD163 ratio, according to the STROBE guidelines." (PMID 34512652, 2021). "We investigated the correlations between CD86 expression and tumor progression in the identified cancer types: SKCM, UVM and LGG." (PMID 33954112, 2021). "Interactions between CTLA-4 and its ligands, CD80 and CD86, inhibit T cell activity and consequently induce tumor progression." (PMID 34298809, 2021). "We observed increased expression of the immune checkpoints PD-1, PD-L1, CTLA-4, and CD86 (CD28L), the expression levels of which associated with antitumor efficacy and tumor regression." (PMID 34461854, 2021). "We first detected intra- and inter-tumoral heterogeneities between TAM subpopulations and their functions, with CD86+ TAMs playing a crucial role in tumor progression." (PMID 33971970, 2021). "DCs have been shown to activate Tregs as well as Th17 cells in MM and promote tolerance to tumor antigens and T-cell evasion via interactions of CD80/CD86 with CD28 on tumor cells." (PMID 33717170, 2021). "CTLA-4 outcompetes the co-stimulatory molecule CD28 for binding to B7-1/CD80 or B7-2/CD86 expressed on the surface of antigen presenting cells, including tumour infiltrating dendritic cells." (PMID 33995362, 2021). "In an A549 lung carcinoma model the presence of CD86+ myeloid cells, which are regarded as a pro-inflammatory M1-like macrophage phenotype, were required to mediate the anti-tumor growth effect of exogenously administered CO to tumor bearing mice." (PMID 33868304, 2021). "Our results showed a modest antitumor effect in all the tumor models evaluated, which correlated with efficient phagocytosis by DC, inducing increased CD86/40 costimulation molecules and releasing TNF-α and IL-12 cytokines." (PMID 33623783, 2021).
tumor (continued). "In tumor environment of activated ccRCC, the proportion of CD86+CSF1R+ monocytes were significantly increased." (PMID 34239350, 2021). "The expression of CD80/CD86 on tumor cells and immunosuppressive cells with the TME, such as MDSCs, makes the CTLA4-CD80/CD86 axis a remarkable target for cancer immunotherapies." (PMID 33868277, 2021). "Unlike rats allocated to surgery, the laser group demonstrated expression of CD8 and B7-2 (CD86) at the untreated tumor border, as well as reduced peritoneal spread." (PMID 34771568, 2021). "Interaction of CTLA4 with CD86 inhibits T cell activation and is a key negative regulator of the immune response to tumor." (PMID 34316327, 2021). "The first was CTLA4, which binds CD80/CD86 to negatively regulate T-cell activation and blockade leads to anti-tumor immune responses." (PMID 34394102, 2021). "The CD86/CD163 ratio tends to have better predictive values than tumor stage in the training (AUC: 0.682 vs 0.654, p=0.538) and validation (AUC: 0.697 vs 0.659, p=0.586) cohorts." (PMID 34512652, 2021). "PD-1 and CTLA-4 binding to their ligands, respectively PD-L1 and CD80/CD86, expressed by tumor and other cells, leads to functional exhaustion and impairs anti-tumor immunity." (PMID 34370787, 2021). "IL-36γ-expressing CAR T cells were able to enhance MHC class II and CD86 expression on splenic macrophages and DCs of tumor-bearing mice, which suggests that IL-36 plays a role in maturation of antigen presenting cells." (PMID 34177932, 2021). "To further verify the infiltration of different macrophages in tumor cells, we examined the expression of CD86 (marker for M1 macrophage) and CD206 (marker for M2 macrophage) in tumor tissues." (PMID 33455085, 2021). "The results indicated that CD86 expression was significantly associated with TME, which has been identified as a key factor in tumor progression and therapeutic response." (PMID 33954112, 2021). "The heatmap demonstrated that CD86 expression was significantly associated with ESTIMATE score, immune score, and stromal score, positively; meanwhile, it negatively correlated to tumor purity, which was consistent with the TIMER analysis." (PMID 34422632, 2021). "Then CD86 (M1 macrophage marker) and CD206 (M2 macrophage marker) were determined using flow cytometry, which showed that overexpression of JMJD1C resulted in a decrease of CD206+ cells and an increase of CD86+ cells in tumor tissues." (PMID 34586733, 2021). "Co-inhibitory CTLA-4 competes with co-stimulatory CD28 to bind to CD80 or CD86 on the surface of APCs to alleviate the anti-tumor immunity of tumor infiltrated T lymphocytes (TILs), such as CD4+T, CD8+T cells and regulatory T cells (Tregs)." (PMID 34858835, 2021). "In an animal experiment, lentinan was proved to increase the number of CD86 + cells infiltrated by tumor to activate DC function." (PMID 33935714, 2021). "CD86 expression profiles among histological and molecular subtypes stratified by tumor grade in LGG were examined." (PMID 33954112, 2021). "Pan-cancer survival analysis established CD86 expression as an unfavorable prognostic factor in tumor progression and survival for LGG." (PMID 33954112, 2021). "Unfortunately, the lack of clinical information fails the validation of correlation between CD86 expression and tumor stage." (PMID 35201503, 2021). "Treg cells has the ability to limit the function of antigen presenting cells by CTLA-4 dependent downregulation of CD80 and CD86 expressions, thereby evading tumor antigen presentation and tumor-specific T cell activation." (PMID 34012451, 2021). "To examine the in vivo anti-tumor activity of CTLA4-T cells toward CD80/CD86-expressing tumors, we developed subcutaneous xenograft models using NOD/SCID/IL2Rg−/− mice." (PMID 33868277, 2021). "Their tumor tissues were stained for CD86, which is often used as a marker for human proinflammatory macrophages." (PMID 33937269, 2021).
tumor (continued). "The efficacy of B7-1 (CD-86) transduced autologous tumor cell vaccine combined with IL-2 was evaluated in a single center phase II trial for the treatment of stage IV renal cell carcinoma." (PMID 33767709, 2021). "High levels of TGFβ1 were positively associated with PD-L1, CD206, and FoxP3 levels in tumor tissues, but inversely with that of CD8, CD56, and CD86." (PMID 34095135, 2021). "Relative to internal DQ-OVA- control, there was a significant downregulation of CD86 on DQ-OVA+ MPs in the tumor, while upregulation of CD80 was observed on DQ-OVA+ colonic MPs." (PMID 34680397, 2021). "The expression of CD83 and CD86 increase significantly after tumor cell lysate loaded into DCs of mice." (PMID 33732237, 2021). "Further, we explored the correlations between CD86 expression and tumor immunity of LGG samples, and Gene Set Enrichment Analysis (GSEA) was performed to reveal potential pathways." (PMID 33954112, 2021). "The expression of CD80 and CD86, two CTLA4 ligands, were observed in ATLL cells and tumor-associated stromal cells." (PMID 33918793, 2021). "We also analyzed the M2-like phenotype of TAMs by detecting CD206-positive cells in spleens and CD206/CD163/CD86/CD80-positive cells in tumor tissues." (PMID 33537094, 2021). "In Lewis-bearing mice model, sophoridine (15 or 25 mg/kg) significantly inhibited the tumour growth and up-regulated the expression of CD86/F4/80 in tumour tissues." (PMID 33718223, 2021). "As shown in the present study, CD86 expression level was significantly correlated with worse survival and it was upregulated as the tumor grade increases in LGG." (PMID 33954112, 2021). "CTLA-4 binds to its ligands CD80 (B7-1) and CD86 (B7-2) and inhibits T-cell activation, negatively regulates T-cell functions, and mediates tumor immunosuppression." (PMID 34943817, 2021). "The maturation status of TIDCs, hence the expression of costimulatory molecules like CD80 and CD86, seems to be determined by the tumor entity." (PMID 33141285, 2021). "Mechanistically, incubation of dendritic cells with tumor MV induced dendritic cell maturation with concordant upregulation of the co-stimulatory molecules CD80 and CD86, increasing their homing to the tumor-draining lymph nodes." (PMID 32731639, 2020). "Combination with anti–CTLA-4 led to tumor regression accompanied by enhanced T cell activity, increase in activated CD86+ monocytes in the tumor, augmentation of pro-inflammatory IFNγ, TNFα, and IL-6 and decrease in immunosuppressive MCP-1 and IL-10 cytokines." (PMID 32793228, 2020). "Furthermore, tumor cells can escape the anti-cancer immunity by activating regulatory T lymphocytes that express cytotoxic T-lymphocyte-associated protein 4 (CTLA-4) competing with CD28 of effector T lymphocytes for binding to CD80/CD86 of antigen presenting cells." (PMID 32610582, 2020). "Among the IRGs filtered, the CTLA-4 promotes immune escape of tumor cells by competitively binding to CD80 and CD86, blocking T cell activation and anti-tumor immune response of the body." (PMID 33031392, 2020). "Administration of anti-CD40 in PDAC-bearing mice did not produce a significant change in the number of TAMs within the tumor, but a transitory change in macrophage activation (i.e., CD86 and MHC class II expression) was seen within 24-48 h of treatment." (PMID 35582441, 2020). "CD80 and CD86 are normally only expressed on APCs, but some tumor cells are able to express these co-stimulatory molecules as well." (PMID 32957644, 2020). "CTLA-4 downregulates T-cell activation and inhibits its anti-tumor immune response by binding to co-stimulatory molecules on DCs (CD40, CD80, and CD86) and suppressing their ability in presenting foreign or tumor antigens." (PMID 32784928, 2020).
tumor (continued). "The frequency of CD80+CD86+ mature BMDCs after co-culture with 4T1 tumour cells pretreated with free OLE was significantly higher that of the control group, indicating that ICD from dying 4T1 cells elicited by OLE can induce DC maturation and immune response." (PMID 33009382, 2020). "The curves of the Cd86 transcription level as well as the tumor cytotoxicity level showed some optimal dose ranges for M2-like macrophage activation." (PMID 32089766, 2020). "Analysis of the M1/M2 profiles demonstrated these microglia showed elevated M1 markers, including MHCII, CD11c, and CD86, indicating that the microglia polarized toward to M1, which is beneficial for an anti-tumor effect." (PMID 32974124, 2020). "As expected, the expression level of HAVCR2, CD40, SIGLEC7, CD86 genes are inversely correlated with tumor purity." (PMID 32021566, 2020). "On the contrary, CD80 and CD86 markers were negatively correlated between tumor‐infiltrating cDC2s and pDCs upon TLR stimulation, reflecting complex cross‐talks within DC subsets." (PMID 33282290, 2020). "Tumor-associated macrophages in Frount-deficient mice also displayed lower expression of the activation markers CD80, CD86 and MHC class II, as well as M2 macrophage marker CD206, compared to those in control mice." (PMID 32001710, 2020). "It is noteworthy that the PTA-expanded Vγ2Vδ2 T cells expressed antigen-presenting cell-related molecules like CD86, HLA-DR, and HLA-DQ, suggesting that tumor antigen-presentation by Vγ2Vδ2 T cells are expected after killing of tumor cells." (PMID 32793196, 2020). "Flow cytometry revealed increased maturation (i.e. CD86) of dendritic cells (DCs) in the meninges and altered antigen loading of DCs in both the tumor and meninges." (PMID 32754281, 2020). "Flow cytometry and immunofluorescence were used to detect the changes of immune cells in the tumor microenvironment and spleen, including M1 (CD11b+F4/80+CD86+CD206-), and M2 (CD11b+F4/80+CD86-CD206+) MΦs, and IFN-γ+CD8+T cells." (PMID 32802195, 2020). "Immune checkpoint receptors, including PD-1 and CTLA4, are expressed on the surface of immune cells, whereas the cognate ligands (PD-L1/PD-L2 and CD86/CD80) are expressed on the tumor cell surface." (PMID 33425739, 2020). "Briefly, the binding of CD28 on T cells to B7-1/B7-2 (CD80/CD86) on antigen-presenting cells (APC) results in co-stimulatory anti-tumor responses." (PMID 33182298, 2020). "cDC1s consistently expressed the highest levels of the co-stimulatory molecule CD86 in all tissues analyzed (spleen, tumor, tdLN)." (PMID 33268774, 2020). "The amounts of M2 (CD163+) and M1 (CD86+) macrophages showed individual variation in the tumor microenvironment." (PMID 32444799, 2020). "We further explored the correlation between PINK1 expression and representative immune markers in LIHC and LUSC, and PINK1 expression was more strongly correlated with tumor-associated macrophage markers such as HLA-G, CD80, and CD86 in LUSC than in LIHC." (PMID 33244455, 2020). "Since inhibitory signaling of PD1 acts directly on the CD28 costimulatory receptor on T cells, 14 we investigated the expression of CD86 (CD28 ligand) on tumor-resident myeloid cells and APCs." (PMID 32690667, 2020). "Incubation with PS1 siRNA-treated CAF-conditioned medium resulted in a significant increase in CD40 and CD86 levels in dendritic cells (p < 0.05), indicating an increase in their ability to present tumor antigens to other effector cell types." (PMID 32587587, 2020). "Transducing tumors with the B7 ligands CD80 or CD86 can enhance anti-tumor immunity by enabling the tumor cells to directly deliver antigenic and costimulatory signals to T and NK cells." (PMID 31452512, 2019). "Expression of MHC class II as well as CD80 and CD86 molecules was also higher on tumor-infiltrating macrophages from Rnf5−/− compared with WT mice." (PMID 30940817, 2019).